PGM3 (phosphoglucomutase 3)
Diseases named in the same sentence as PGM3 in open-access papers (continued):
Sharing a sentence is not in itself a finding about the gene and the disease.
Allergy (2 papers, 2016 to 2025). An allergy is an immune response or reaction to substances that are usually not harmful. "For instance, allergy is known to be frequent in people with a CARD11 (AD DN) deficiency, a DOCK8 deficiency or a PGM3 deficiency." (PMID 41142799, 2025). "Moreover, our data combined with a recent study show that IgE glycoproteomic spectra are similar among healthy controls, patients with allergy and the patient with HIES caused by PGM3 mutation." (PMID 26687240, 2016).
bone marrow failure (2 papers, 2015 to 2025). "Hypomorphic Pgm3 function in mice results in a bone marrow failure phenotype and a similar phenotype was observed among three patients harboring deleterious PGM3 mutations, who presented early in life with T−B−NK+ severe combined immunodeficiency (SCID)." (PMID 26125015, 2015).
Cohen syndrome (2 papers, 2018 to 2023). Cohen syndrome (CS) is a rare genetic developmental disorder characterized by microcephaly, characteristic facial features, hypotonia, non-progressive intellectual deficit, myopia and retinal dystrophy, neutropenia and truncal obesity. "Developmental delay is indicated in 3MC syndrome, LAD type 2, Cohen syndrome, Kabuki syndrome, Barth syndrome, P14 deficiency, adenosine deaminase acting on RNA 1 (ADAR1) deficiency, HIES with PGM3 mutations, PNP deficiency, MKD, DGS, NBS, and ITCH deficiency." (PMID 37102642, 2023).
developmental delay (2 papers, 2018 to 2020). "Patients with PGM3 mutations are reported to carry a high risk of early onset neurological impairment including developmental delay, ataxia, dysarthria, psychomotor retardation, hypotonia, sensorineural hearing loss, seizures and myoclonus." (PMID 30026765, 2018). "Recently, PGM3 mutations have also been identified as a cause of CDG, usually exhibiting severe skeletal dysplasia, congenital malformations, and developmental delay." (PMID 33193641, 2020).
osteosarcoma (2 papers, 2022 to 2024). A usually aggressive malignant bone-forming mesenchymal neoplasm, predominantly affecting adolescents and young adults. "Four HBP-related genes (GFPT, GNPNAT, PGM3, and UAP1) can be used to guide immunologic and targeted therapies for osteosarcoma, with significant predictive value for osteosarcoma prognosis." (PMID 38915778, 2024). "We constructed an HBP-related gene signature containing five key genes (GPI, PGM3, UAP1, OGT, MGEA5) which showed a remarkable prognostic value for predicting prognosis and can guide immunotherapy and targeted therapy for osteosarcoma." (PMID 36275679, 2022).
severe combined immunodeficiency (2 papers, 2015 to 2022). Severe combined immunodeficiency (SCID) comprises a group of rare monogenic primary immunodeficiency disorders characterized by a lack of functional peripheral T lymphocytes resulting in early-onset severe respiratory infections and failure to thrive. "Phosphoglucomutase 3 (PGM3) deficiency – This is an AR form of HIES, was first described in 2014 in patients who were previously diagnosed with HIES or severe combined immunodeficiency." (PMID 35185921, 2022).
autism spectrum disorder (1 paper, 2025). A spectrum of developmental disorders that includes autism, and Asperger syndrome. "Neurologically, she was diagnosed with mild autism spectrum disorder and learning disability, findings consistent with reported neurological involvement in PGM3 deficiency." (PMID 40698220, 2025).
Autosomal dominant hyper-IgE syndrome (1 paper, 2019). 2000 IU/ml), recurring staphylococcal skin abscesses, and recurrent pneumonia with formation of pneumatoceles. "For others, IgE plasma levels are elevated: DOCK8 deficiency, autosomal dominant hyper-IgE syndrome (AD-HIES) Job’s syndrome, Comel-Netherton syndrome, PGM3 deficiency, IPEX (immune dysregulation, polyendocrinopathy, enteropathy X-linked) and Tyk2 deficiency." (PMID 31290545, 2019).
Bloom syndrome (1 paper, 2023). Bloom syndrome (BSyn) is a rare chromosomal breakage syndrome characterized by a marked genetic instability associated with pre- and postnatal growth retardation, facial sun-sensitive telangiectatic erythema, increased susceptibility to infections, and predisposition to cancer. "Mild to moderate intellectual disability is seen in DGS, b‐actin deficiency, HIES with PGM3 mutations, Kabuki Syndrome, Bloom syndrome, NBS, CHD, and ICF syndrome." (PMID 37102642, 2023).
congenital disorder of glycosylation (1 paper, 2020). Congenital disorder of glycosylation (CDG) is a fast growing group of inborn errors of metabolism characterized by defective activity of enzymes that participate in glycosylation (modification of proteins and other macromolecules by adding and processing of oligosaccharide side chains). "Previously, PGM3 mutations were associated with immunodeficiency-23 (IMD23, OMIM# 615816) and/or congenital disorder of glycosylation (CDG) that is occasionally accompanied by seizures." (PMID 33193641, 2020).
epilepsy (1 paper, 2020). A brain disorder characterized by episodes of abnormally increased neuronal discharge resulting in transient episodes of sensory or motor neurological dysfunction, or psychic dysfunction. "Taking together the evidence that PGM3 gene is expressed in brain and associated with neurodevelopmental disturbance, the PGM3 gene is suggested to be potentially a candidate pathogenic gene of epilepsy." (PMID 33193641, 2020). "Taking together the data from the gene expression profile and the PGM3 deficiency animal model, it is suggested that PGM3 gene is potentially a candidate pathogenic gene of epilepsy." (PMID 33193641, 2020). "The evidence suggests that PGM3 gene is potentially a candidate pathogenic gene of epilepsy." (PMID 33193641, 2020). "The genetic and molecular evidence from the present study implies that the PGM3 variants identified in IFE patients lead to defects of the PGM3 gene, suggesting that the PGM3 gene is potentially associated with epilepsy." (PMID 33193641, 2020).
glioblastoma (1 paper, 2025). The most malignant astrocytic tumor (WHO grade IV). "Furthermore, chronic temozolomide exposure activates the HBP-PGM3 axis to elevate O-GlcNAcylation, which inhibits ferroptosis in glioblastoma; this chemoresistance can be reversed by targeting PGM3, thereby reactivating ferroptosis and suppressing tumor growth." (PMID 41350524, 2025).
glioma (1 paper, 2025). A benign or malignant brain and spinal cord tumor that arises from glial cells (astrocytes, oligodendrocytes, ependymal cells). "PGM3 expression was significantly higher in WHO grade III compared to grade II patients (p < 0.01) and in WHO grade IV compared to grade III patients (p < 0.01), indicating a potential association between PGM3 expression and glioma grading." (PMID 40772310, 2025). "Stratifying patients by PGM3 expression levels revealed that high PGM3 expression was significantly associated with worse clinical outcomes in both overall glioma patients and a subset of GBM patients." (PMID 40772310, 2025). "Our results suggest that PGM3 is a potential therapeutic target in glioma." (PMID 40772310, 2025).
Kabuki syndrome (1 paper, 2023). Kabuki syndrome (KS) is a multiple congenital anomaly syndrome characterized by typical facial features, skeletal anomalies, mild to moderate intellectual disability and postnatal growth deficiency. "Scoliosis is demonstrated in HIES with PGM3 mutations and Kabuki syndrome." (PMID 37102642, 2023).
lung adenocarcinoma (1 paper, 2022). A carcinoma that arises from the lung and is characterized by the presence of malignant glandular epithelial cells. "Actually, targeting GFPT2 by azaserine and targeting PGM3 by FR054 can specifically inhibit KRAS/LKB1 combined mutant lung adenocarcinoma cells, respectively." (PMID 36158580, 2022).
lung carcinoma (1 paper, 2022). "Collectively, our findings elucidate another metabolic liability in KL co-mutant lung cancer, PGM3 dependence, and explore how PGM3 inhibition (e.g., FR054) can be used to exploit this vulnerability." (PMID 35011738, 2022).
myeloid neoplasm (1 paper, 2023). Proliferation of myeloid cells originating from a primitive stem cell. "Among the thirty-one patients, five (16.1%) had causative germline variants predisposing them to myeloid neoplasms (three with GATA2 variants and one each with PGM3 and ETV variants)." (PMID 38137719, 2023). "Among the thirty-one patients, five (16.1%) had causative germline variants predisposing them to myeloid neoplasms in the GATA2, PGM3, and ETV6 genes, and all of these identified variants have been previously reported." (PMID 38137719, 2023).
Sepsis (1 paper, 2025). Sepsis is defined as life-threatening organ dysfunction caused by a dysregulated host response to infection. "Integrating WGCNA with three machine learning algorithms, we identified six diagnostic genes—PGM3, GDF15, GART, GFOD2, E2F2, and ATP1B2—associated with sepsis-induced ALI, which were validated in clinical samples by Western blotting." (PMID 41142807, 2025).
skin infection (1 paper, 2020). An inflammatory process affecting the skin, caused by bacteria, viruses, parasites, or fungi. "In humans, PGM3 mutations were initially associated with IMD-23 characterized by recurrent respiratory, skin infections beginning in early childhood, and notably increased serum IgE in laboratory studies." (PMID 33193641, 2020).
cancer (8 papers, 2010 to 2025). A tumor composed of atypical neoplastic, often pleomorphic cells that invade other tissues. "Some glycosylation enzymes (GALNT7, GCNT1, TAP1, PGM3, etc.)are under the control of AR and link to the synthesis of cancer-associated glycans such as sialyl-Tn (sTn), sialyl LewisX (SleX)." (PMID 35853851, 2022). "Consistently, similar effects were observed in the two cancer cell models after treatment with the PGM3 inhibitor (unpublished data by Prof. Chiaradonna)." (PMID 39776909, 2024). "PGM3, on the other hand, is an N-acetylglucosamine triphosphatase involved in the biosynthesis of the amino alanine, and it plays an anti-cancer role." (PMID 31582909, 2019). "PGM3, a metabolic enzyme within HBP, has recently been implicated in various cancers." (PMID 40772310, 2025). "While studies in other cancers have primarily focused on GFPT1, the rate‐limiting enzyme of the HBP, the role of PGM3 has been largely overlooked." (PMID 40772310, 2025). "Key enzymes such as GFAT1/GFAT2, GNPNAT1, PGM3, and UAP1 are frequently upregulated in various cancers, correlating with increased UDP‐GlcNAc production and global O‐GlcNAcylation." (PMID 40772310, 2025). "Before examining the anti-cancer effect of FR054 in NSCLC, we aimed to confirm whether FR054 effectively inhibits PGM3 activity." (PMID 35011738, 2022). "In some datasets where GFAT expression was not significantly increased, one of GNPNAT1, PGM3, or UAP1 was highly expressed in cancer tissues." (PMID 31645543, 2019).
tumor (8 papers, 2022 to 2026). "Suppressing PGM3 reduces protein glycosylation, causes a sustained unfolded protein response, downregulates the pro-tumor EGFR-Akt axis, and ultimately leads to cell death." (PMID 36699061, 2022). "Downregulation of PGM3 inhibited BCa tumor growth and metastasis by suppressing energy metabolism pathways, including glycolysis and oxidative phosphorylation (OXPHOS)." (PMID 41942430, 2026). "PGM3 expression was significantly higher in tumor cells compared to immune, stromal, and other cell types." (PMID 40772310, 2025). "Genetic suppression and pharmacological inhibition of PGM3 by FR054, a competitive inhibitor of PGM3, impaired tumor growth and promoted the death of KL co-mutant NSCLC cells both in vitro and in vivo." (PMID 35011738, 2022). "Genetic or pharmacologic suppression of PGM3 reduced KRAS/LKB1 co-mutant tumor growth in both in vitro and in vivo settings." (PMID 35011738, 2022). "PGM3 silencing also significantly decreased the number of tumor-associated glycan structures in KL co-mutant but not K mutant cells." (PMID 35011738, 2022). "PGM3 expression was significantly higher in tumor tissues compared to normal tissues in COAD, DLBC, GBM, LGG, READ, and THYM, while lower in ACC, AML, and OV, suggesting an oncogenic role for PGM3 in GBM." (PMID 40772310, 2025). "The combination of PGM3 inhibitor FR054 and GEM increases chemosensitivity and effectively inhibits xenograft tumor growth." (PMID 36699061, 2022). "Notably, although PGM3 catalyzes a reversible reaction within the HBP, recent evidence suggests that PGM3 knockdown or inhibition significantly reduces tumor cell proliferation and decreases O‐GlcNAcylation levels." (PMID 40772310, 2025). "However, in the present NSCLC study, neither PGM3 silencing nor FR054 treatment induced ER stress (Data not shown), suggesting that the underlying death mechanisms may be different, possibly due to tumor heterogeneity derived by different tissue of origin." (PMID 35011738, 2022). "Similarly, another independent GSE3167 dataset also displayed the increased mRNA expression levels of GFPT1, PGM3, and UAP1 and the decreased GFPT2 level in tumor tissues, while the data of GNPNAT1 gene were not available in this dataset." (PMID 36158580, 2022).
skeletal dysplasia (7 papers, 2018 to 2026). Any Mendelian diseases that affects growth and development of the skeleton. "In some of them (ALG12-CDG, ALG3-CDG, ALG9-CDG, PGM3-CDG, SLC35D1-CDG), a severe prenatal-onset skeletal dysplasia was observed and associated with an early death." (PMID 34441372, 2021). "Unlike the majority of reported PGM3 deficient patients she lacked skeletal dysplasia and had normal neurocognitive development." (PMID 30157810, 2018). "There is a group of CDGs, including ALG12-CDG, ALG3-CDG, ALG9-CDG, ALG6-CDG, PGM3-CDG, CSGALNACT1-CDG, SLC35D1-CDG, and TMEM-165 with well-defined skeletal dysplasia." (PMID 34441372, 2021). "Contrary to PMM2-CDG, skeletal dysplasia was well characterized in other CDGs, including ALG12-CDG, ALG3-CDG, ALG9-CDG, ALG6-CDG, PGM3-CDG, CSGALNACT1-CDG, SLC35D1-CDG and TMEM165-CDG." (PMID 34441372, 2021). "Contrary to PMM2-CDG, all remaining CDG, including ALG12-CDG, ALG3-CDG, ALG9-CDG, ALG6-CDG, PGM3-CDG, CSGALNACT1-CDG, SLC35D1-CDG and TMEM-165, are characterized by well-defined skeletal dysplasia." (PMID 34441372, 2021).
neurologic disorders (2 papers, 2022 to 2023). "Furthermore, it was discovered that several targets, such as DLG2, ETV5, PGM3, and ALPK1, were key regulators of neurological diseases." (PMID 36644780, 2023).
infectious disease (1 paper, 2024). A disorder directly resulting from the presence and activity of a microbial, viral, or parasitic agent in humans. "Furthermore, the enzymatic role of PGM3 in generating UDP-GlcNAc and in broadly affecting the function of glycosylated proteins in numerous cell types may be involved in the pathogenesis of atopic and infectious diseases." (PMID 39776909, 2024).
metabolism disorders (1 paper, 2022). "PPARA, PPARGC1A, and PPARGC1B, which are involved in the fatty acid oxidation of PLN-KO hiPSC-CMs, began to decline at day 30, while genes involved in glucose utilization, such as GNPNAT1, PGM3, and GFPT1, were upregulated, indicating that energy metabolism disorders began to occur." (PMID 35334215, 2022).
PGM3 also shares sentences with these, for which no sentence is quoted: Autosomal recessive hyper-IgE syndrome (2 papers); bladder cancer (2); dermatitis (2); Loeys-Dietz syndrome (2); melanoma (2); Wiskott-Aldrich syndrome (2); -linked syndrome (1); 3MC syndrome (1); anemia (1); angiosarcoma (1); antibody deficiency (1); Ataxia (1); autoimmune disease (1); autoimmune lymphoproliferative syndrome (1); autosomal dominant Job ́s syndrome (1); avian influenza (1); Barth syndrome (1); bullous pemphigoid (1); chronic granulomatous disease (1); combined immunodeficiency (1); congenital malformations (1); cyst (1); cystic fibrosis (1); Desbuquois dysplasia (1); diffuse large B-cell lymphoma (1); Enteropathy (1); eosinophilia (1); focal epilepsy (1); fungal infections (1); genetic disorders (1).
A further 24 diseases each share a sentence with PGM3 in 1 paper.